ANKRD36C (ankyrin repeat domain 36C)
Synonyms: DKFZp667P0924
Tractability: PROTAC: ubiquitination databases record sites on it.
Gene: Protein-coding gene on chromosome 2 (95,836,919 to 95,991,831, reverse strand). Ensembl gene ENSG00000174501.
Subcellular location (Human Protein Atlas): Cytosol; Nucleoplasm
Gene Ontology:
Molecular function: ion channel inhibitor activity
Genetic constraint (gnomAD): Loss-of-function variants: 56 observed, 205.65 expected, observed/expected ratio (o/e) 0.27, 90% interval 0.22 to 0.34. The synonymous counts are far from expectation, so gnomAD's model fits this gene poorly and the ratio says little. Missense variants: 1,373 observed, 1,642.3 expected, observed/expected ratio (o/e) 0.84, 90% interval 0.8 to 0.87. Synonymous variants: 456 observed, 547.17 expected, observed/expected ratio (o/e) 0.83, 90% interval 0.77 to 0.9.
Homologues: Orthologues: chimpanzee ANKRD36C (85% identical), dog ANKRD31 (7% identical), tropical clawed frog ankrd31 (5% identical), Drosophila melanogaster pain (4% identical). Paralogues in human: ANKRD36 (82% identical), ANKRD36B (59% identical), ANKRD31 (8% identical).
Diseases named in the same sentence as ANKRD36C in open-access papers:
ANKRD36C is named in the same sentence as 4 diseases in open-access papers, as found by Europe PMC text mining. Sharing a sentence is not in itself a finding about the gene and the disease. The quoted sentences say what the papers report.
tumor (3 papers, 2022 to 2024).
cancer (2 papers, 2021 to 2024). A tumor composed of atypical neoplastic, often pleomorphic cells that invade other tissues. "ANKRD36 has been reported to be coexpressing and interacting with other genes on locus 2q11.2, including ANKRD36C, ITPRIPL1, FAHD2B, FAM178B and CNNM3, which shows that ANKRD36 is involved in some important biological networks associated with cancers." (PMID 34827175, 2021).
ANKRD36C also shares sentences with these, for which no sentence is quoted: atherosclerosis (1 paper); autoimmune disease (1).